CD5 (CD5 molecule)
Diseases named in the same sentence as CD5 in open-access papers (continued):
Sharing a sentence is not in itself a finding about the gene and the disease.
tumor (continued). "CD5+ cDC2 can prime CD5hi T cells in the context of immune checkpoint blockade therapy, facilitating tumor rejection." (PMID 39399662, 2024). "A great deal of work has also gone into the utilization of the anti-tumor effect of CD5-targeting fully human heavy-chain variable (FHVH) domains, which bind directly to different epitopes of the CD5 antigen." (PMID 39410047, 2024). "Following engraftment with Eμ-TCL1 spleen-derived lymphocytes, mice were monitored until tumor expansion was witnessed (≥10% CD45+CD19+CD5+ peripheral blood lymphocytes [PBLs]), then randomly assigned to receive OPN5 or vehicle equivalent (VEH)." (PMID 38775157, 2024). "Immunohistochemical staining of the tumor cells showed positivity for CD2, CD3, CD4, CD5, CD25 and CD45 and partial loss of CD7." (PMID 36975591, 2023). "The CD5 CAR-T cells efficiently lysed CD5+ malignant T cell lines and primary cells in vitro, and tumor progression was controlled in vivo." (PMID 36624522, 2023). "Most of the tumor cells within the lymphoid stroma were CD5-positive, CD3-negative, and terminal deoxynucleotidyl transferase (TdT)-negative." (PMID 39516978, 2023). "In the squamous cell component, the tumor cells were focally positive for CD5, p40, and CK5/6, whereas the glandular component was focally positive for CD5 and CK7." (PMID 39516971, 2023). "Retrospective analyses of tumor patient cohorts treated with checkpoint inhibitors should be performed to clarify CD5’s therapeutic impact." (PMID 37230972, 2023). "Aberrant CD5 co-expression by the B cells and cyclin D1 nuclear staining is important to differentiate these tumours from EMZL." (PMID 35882984, 2023). "Next, consistent with our murine data, we excluded CD56 and CD5 in order to exclude any NK cells or ILC-3s or tumor-defined ILC-1s in cSCC from our analysis." (PMID 37098069, 2023). "The authors validated the necessity of CD5 on both DCs and T cells for noteworthy tumor regression induced by immune checkpoint inhibitor treatment (anti-PD-1 or anti-CTLA-4)." (PMID 37230972, 2023). "CD5 CAR-NK-92 cells displayed specific cytotoxic responses against CD5+ cell lines and CD5+ primary tumor cells in vitro and significantly inhibited disease progression in xenograft mouse models." (PMID 35493522, 2022). "This idea is supported by changes in the tumor immunophenotype over time during ibrutinib therapy as sIgM, eIgM and CD5 expression levels initially increase then fall in the longer term." (PMID 35902732, 2022). "Our results show that CD3-CAR-T is more active than CD5-CAR-T to eliminate malignant T cells in vitro, however, CD3-CAR-T were less efficient to eliminate tumor cells in vivo, while CD5-CAR-T had antitumor activity in a diffuse xenograft model." (PMID 35158792, 2022). "Another type of B-cell-derived tumor is mantle cell lymphoma that usually originates from the clonal expansion of naïve CD5 B cells located in the mantle zone of secondary lymphoid follicles." (PMID 35203305, 2022). "Tumor-infiltrating B cells that express high levels of CD5+ have been shown to promote tumor angiogenesis/growth through lymphotoxin production and have been associated with poorer clinical outcomes in HCC." (PMID 36618354, 2022). "In the present study, immunophenotyping showed the intermediate- to large-sized cells to be of T cell origin with strongly CD3 and CD8 positive; CD5 was positive in scattered cells within the tumor and focally positive cells for CD30 biomarker were observed." (PMID 36451465, 2022). "Signet ring cell-like morphology combined with positive IHC staining for CK7, CEA and CD5 further verified the thymic origin of the tumor." (PMID 36482538, 2022). "Researchers made CD5/CD7 CAR-T cells that showed anti-tumor substantial effects in malignant T cell lines such as Jurkat, CCRF-CEM, MOLT, and in xenogeneic mouse models established using CCRF-CEM-ffLuc cell injections." (PMID 36261831, 2022).
tumor (continued). "The CAR-NK framework greatly improved the efficacy of CARs leading to increased degranulation, cytokine secretion and elimination of the tumor xenograft by CD5-CAR-NK effector cells." (PMID 35158792, 2022). "As IL-15 strengthens the anti-tumor response, we have modified CD5 CAR to secrete an IL-15/IL-15sushi complex." (PMID 33410096, 2021). "Collectively, FHVH3/VH1 CAR-T cells demonstrated potent and specific tumor-killing activity against CD5+ cells." (PMID 34274536, 2021). "One unique and particularly aggressive presentation is leukemic transformation with CD5 positivity, which leads to systemic symptoms, a relatively high peripheral tumor load, and higher rates of CNS involvement." (PMID 34327076, 2021). "They demonstrated that CD5CAR-NK-92 cells specifically target CD5+ tumor cell lines and CD5+ primary tumor cells in vitro and exert consistent, potentially cytotoxic effects." (PMID 34215336, 2021). "In this brief research report, we describe a peptide-based single-cell sorting using as bait the IgBCR of tumor cells; in the next step, we performed a quantitative analysis of CD5 expression by qRT-PCR related to the expressed IgBCR." (PMID 34222027, 2021). "Their results showed that the expression of CD5 was significantly increased at the junction of tumor and stroma, and its expression in lymphocytes was significantly higher than in tumor cells." (PMID 33907159, 2021). "As expected, FHVH3/VH1 CAR-T cells exhibited stronger CD5 antigen-specific degranulation and killing ability than either H65, FHVH1, or FHVH3 CAR-T cells, especially for tumor cells with moderate expression of CD5 antigen." (PMID 34274536, 2021). "CD5KO anti-CD5 CAR-T cells selectively killed tumor cells expressing different CD5 antigen densities in a dose-dependent manner." (PMID 34274536, 2021). "The tumor cells characteristically show co-expression of one or more natural killer (NK)-cell-associated antigens (CD16, CD56, or CD57) and decreased CD2, CD5, or CD7 expression." (PMID 33673033, 2021). "CD5-IL15/IL15sushi CAR T cells demonstrated potent anti-tumor efficacy in vitro against a CD5-positive cell line." (PMID 33410096, 2021). "First, we determined CD5 levels in T cell subsets isolated from lymphoid organs and the tumor microenvironment." (PMID 33584650, 2020). "Together, these results reveal that the presence of poorly immunogenic tumor homografts in mice leads to elevated CD5 on T cells in lymph nodes, similar to the increase in CD5 seen after ex vivo stimulation of the TCR/CD3 complex on CD8+ T cells." (PMID 33584650, 2020). "Downregulation of CD5 was associated with an increased fraction of activated CD4+ and CD8+ T cells in the tumor microenvironment." (PMID 33584650, 2020). "This suggests the reduced CD5 in TILs, particularly in CD8+ TILs, is associated with increased effector function and enhanced anti-tumor immunity." (PMID 33584650, 2020). "We report that T cell CD5 levels were higher in CD4+ T cells than in CD8+ T cells in 4T1 tumor-bearing mice, and that high CD5 levels on CD4+ T cells were maintained in peripheral organs (spleen and lymph nodes)." (PMID 33584650, 2020). "We found different patterns of CD5 expression in T cell isolated from different tissues in mice bearing tumor homografts." (PMID 33584650, 2020). "Circulating CD5+ B cells were decreased in patients with bladder cancer, probably due to either infiltration of these cells into the tumor or to the effect of T cells or cytokines." (PMID 33287301, 2020). "It is possible that the presence of IL-7 and IL-21 in the tumor microenvironment reduced CD5 by modulating transcriptional and/or posttranscriptional control mechanisms although that possibility is not specifically addressed by our data." (PMID 33584650, 2020).
tumor (continued). "Remarkably, circulating class‐switched memory B cells (CD27+IgD−) showed a strong inverse correlation with CD68 staining grade, while intermediate monocytes (CD14++CD16+) negatively correlated with CD3+ and CD5+ cell density in the tumor." (PMID 33024560, 2020). "The levels of CD5 on the surfaces of naïve T cell and T cell from 4T1 tumor homograft-harboring mice showed different patterns of expression." (PMID 33584650, 2020). "A small fraction of T cells recruited to the tumor microenvironment display reduced CD5 levels compared to T cells in lymph nodes and spleens." (PMID 33584650, 2020). "This suggests that the fraction of CD8+ TILs with reduced CD5 levels in the tumor microenvironment have higher levels of activation than CD5high/CD8+ TILs, while the situation with CD4+ TILs is more complex." (PMID 33584650, 2020). "Tumor cells exhibited an expression of CD5 (two cases), CD8 (three cases), CD56 (six cases), CD57 (three cases), and Granzyme B (eight cases)." (PMID 32372136, 2019). "For our analysis, we used a cohort of seven TCL1 mice that had developed high tumor loads of CD5/CD19 double positive CLL cells (mean 86.9% ± 6.1%)." (PMID 30262843, 2019). "The tumor size in CD5-/- BMDC immunized mice was less than the half of that in WT DC immunized mice at the indicated times of measurements." (PMID 31491023, 2019). "Results show tumor size in mice immunized with OVA pulsed WT or CD5-/- BMDC were significantly lower than controls; importantly, CD5-/-DC were more potent than WT DC in the induction of anti-tumor immunity." (PMID 31491023, 2019). "Immunohistochemical analysis revealed tumor cells were positivity for Bcl2, CD5, and p40, while infiltrated lymphocytes were positive for CD3 and negative for CD99." (PMID 31655916, 2019). "The results support a regulatory role for CD5 in DC in the context of proliferation of CD4+ and CD8+ T cells and demonstrate that blockade of CD5 signals in DC enhances anti-tumor immune responses." (PMID 31491023, 2019). "A total of 405 cases of DLBCL were investigated for CD5 expression on tumor cells, and 30 cases of CD5+ DLBCLs, consisting of one case transformed from CLL and 29 de novo cases (29 of 405, 7.2%), were identified." (PMID 31644584, 2019). "After 5 h of stimulation, the proportion of Bregs, which were found to be predominantly CD5+CD24hi, was slightly higher in the tumor tissue (0.98 ± 0.78%) compared to matched peripheral blood B cells (0.46 ± 0.12%) and control tonsils (0.41 ± 0.09)." (PMID 31623665, 2019). "Tumor cells appear as CD5+ mature small lymphocytes, of which a small portion present as the blastic type." (PMID 30608386, 2019). "For example, IL-6 binding to CD5+ B cells promoted tumor growth by activating STAT3 in mouse tumor models, and were observed to be correlated with phosphorylated STAT3 in multiple human tumors, including NSCLC50." (PMID 29844447, 2018). "The tumor cells in PCALCL possess an activated T-cell phenotype and express CD2, CD4, and CD45RO, with a loss of CD2 and CD5 occurring variably." (PMID 29915722, 2018). "Consistently, the tumor-infiltrating TIM-1+B cells showed increases in the expression levels of CD5, CD27 and CD38 compared to the TIM-1−B cells." (PMID 30526680, 2018). "Although many studies demonstrated that 4-1BB CAR is safe with increased persistence, in case of CD5+ tumor targeting, CD5-4-1BB CAR showed reduced efficacy compared with CD5-CD28z CAR due to enhanced T cell fratricide." (PMID 30713539, 2018). "To explore the impact of CD40L or AID-deficiency on BCR usage in CLL, we performed IghV and IglV sequence analyses in selected CLL samples with high tumor load (>95% IgMb+CD5+CD43+CD19+ CLL-like cells)." (PMID 30271400, 2018). "Next, we analyzed IghV and IglV sequences in CLL samples with high tumor load (>95% IgMb+CD5+CD43+CD19+ CLL-like cells)." (PMID 30271400, 2018).
tumor (continued). "Taken together, the results further illustrate the putative regulatory role of CD5-mediated interactions in anti-tumor immune responses, which would be at least in part fostered by NK cells." (PMID 29296231, 2017). "This in turn promotes IL-10 expression and self-expansion of regulatory CD5+CD19+ B cells (B10) in tumor microenvironment, resulting in promotion of tumor growth." (PMID 29296231, 2017). "Based on these descriptions, we utilized a similar CD5 depletion strategy to deplete CD5high cells from PBMCs obtained from multiple donors including healthy dog volunteers, tumor-bearing dogs, and laboratory beagles." (PMID 29254507, 2017). "Interaction of Sema4D-expressing CD5+ B-cells or leukemic-B-cells with Plexin-B1-expressing cells led to improved tumor survival." (PMID 28003812, 2016). "As to immunohistochemistry, the tumor cells were positively immunoreactive for CD5 in 10 (71.4%) patients, partial positively in 2 (14.3%) patients and weakly positively in 2 (14.3%) patients." (PMID 27626313, 2016). "Eighteen hours later, significant cooperative effects of these two drugs were demonstrated in the tumor cells (CD45+CD19+CD5+ cells)." (PMID 26310857, 2015). "CXCR4, a chemokine receptor involved in tumor cell homing to bone marrow and lymph node was expressed at higher levels in CD5+ compared with CD5− DLBCL (P= .05)." (PMID 25760242, 2015). "We examined the apoptosis of tumor cells (CD45+CD19+CD5+κ+ or CD45+CD19+CD5+λ+) and normal cells (CD45+CD19−) after treatment of single drug or two-drug combination." (PMID 26310857, 2015). "Almost 75% of CD5+ DLBCL patients had concurrent overexpression (≥70% of the tumor cells) of antiapoptotic Bcl-2, an unfavorable biomarker." (PMID 25760242, 2015). "Expression of CD5 was noted on most tumor cells of CD5+ DLBCL; 67% of CD5+ tumors had >80% of the tumor cells positive for CD5." (PMID 25760242, 2015). "The role of CD5 as a negative regulator of TCR signaling is well established and selective activation of variant CD5-negative T cell clones by tumour cells expressing low levels of HLA-class I/antigenic peptide complexes illustrates its biological relevance." (PMID 25237383, 2014). "Immunohistochemical examination of CD5, lambda, and kappa expressions revealed that the primary tumor was positive for CD5, kappa, and lambda, but the recurrent tumor was weakly positive for CD5 and kappa." (PMID 21892966, 2011). "In relation to our tumour model system, it is interesting to note that the CD5 molecule was previously shown to act as negative regulator of T or B cells." (PMID 21504579, 2011). "Immunophenotyping showed coexpression of CD20 and CD5 in all cases and negativity of the tumour cells for CD23." (PMID 16189522, 2005). "However, the tumoricidal activity of iCAR-Ms is highly related to CD5 density on tumor cells and depends on high dose treatment in vivo." (PMID 41943855, 2026). "To evaluate whether TIL present in the infusion product were also reactive toward CLL antigens, we first isolated CD5+CD19+ B cells from peripheral blood mononuclear cells (PBMCs) collected at the time of tumor harvest and before obinutuzumab administration." (PMID 41333460, 2025). "This study demonstrates that CD5 expression in CTCL is largely dependent on lesion type, with malignant CD4 T cells from patch/plaque MF lesions showing elevated CD5 transcript levels compared to malignant CD4 T cells from MF tumor lesions and healthy control CD4 T cells." (PMID 41226451, 2025). "Our study highlights the clinical relevance of further investigation of possible mechanisms through which CD5 expression on epithelial cells may influence tumor behavior." (PMID 40242668, 2025). "Thirteen cases (36%) had CD5 staining in 50% or more tumor cells, considered positive staining." (PMID 40242668, 2025). "Furthermore, it is unclear which criteria for CD5 expression in tumor cells and which CD5 antibody clone was used in the prior study." (PMID 40242668, 2025).
tumor (continued). "We demonstrate conversion of CD5+/−CD1c+CD14− cDC2s to CD14+ cDC2s by tumor-associated factors, whereas monocytes failed to express CD1c under similar conditions." (PMID 38242119, 2024). "Importantly, FACS analysis revealed a significant increase in CD19-B220+CD5+CD1d- cells in the livers of μMT mice at week 19 after tumor induction." (PMID 39611128, 2024). "CD3 and CD5 reactions only detected T lymphocytes in very low numbers among the tumor cells." (PMID 39768757, 2024). "CD5 blockade with anti-CD5 monoclonal antibody or CD5 knockout could be therapeutically beneficial to enhance T cell-mediated anti-tumor immunity." (PMID 39462383, 2024). "We did not detect statistically significant associations between CD5 positivity and extranodal disease (p = 0.09), tumor size (p = 0.29), or ECOG status (p = 0.37) at presentation." (PMID 39410047, 2024). "Blocking CD5 function may have therapeutic potential in treatment of cancer by enhancing cytotoxic T lymphocyte recognition and ablation of tumour cells." (PMID 38487537, 2024). "Moreover, depletion of CD5-expressing DCs in tumor-bearing mice led to poorer response to anti-PD-1 than in control mice." (PMID 38261139, 2024). "The screening of immortalized CD5+ hybridomas, derived from peritoneal B cells of a naive Balb/c mouse, revealed that some of the secreted IgMs were able to recognize NeuGcGM3 ganglioside and tumor cells expressing this antigen." (PMID 38629061, 2024). "Tumor reactive antibodies may also derive from an innate-like population of B cells characterized by CD5 expression (also called B-1a cells) in humans and their Ly-1 expressing counterparts in mice." (PMID 37965337, 2023). "Taking the demonstrated utmost importance of CD5 into account, its induction by immune checkpoint inhibitors could restore tumor-suppressed DC activity via inducing CD5 expression and the proliferation of CD5+ DCs." (PMID 37230972, 2023). "Moreover, these anti-CD5 CAR-T cells effectively suppressed tumor growth in in vivo models derived from cell lines, known as cell line-derived xenograft (CDX) mice models." (PMID 38143760, 2023). "Notably, the pathological examination found high levels of necrosis in the resected tumor, and flow cytometry analysis indicated a significant increase in the ratio of CD5+ and CD5− B lymphocytes in the peripheral blood." (PMID 36721173, 2023). "Immunohistochemically, the tumor cells stained positive for CD5." (PMID 39516971, 2023). "Tumor growth was assessed by measuring the percentages of CD5+/CD7+ PDX cells in total PBMC." (PMID 36978873, 2023). "CD5/CD7 bispecific CAR-T cells are protective in the heterogeneous xenograft tumor model." (PMID 35332132, 2022). "All tumors that expressed CD5 in ≥50% of tumor cells also expressed CD117 in ≥10% of tumor cells." (PMID 35565429, 2022). "Tumor cells were frequently CD5 positive (52%) with a non‐germinal center origin (86%)." (PMID 35538643, 2022). "Having demonstrated that FHVH1 and FHVH3 bind different CD5 antigenic epitopes, we hypothesized that the use of FHVH1 and FHVH3 in tandem may both enhance the efficacy and reduce the risk of tumor escape caused by antigenic mutations." (PMID 34274536, 2021). "Many tumour cells expressed CD5- and anti-CD3-staining marked T-lymphocytes." (PMID 34814897, 2021). "Self-activation and fratricide caused by expression of CD5 antigen on the anti-CD5 CAR-T cells may contribute to poor persistence, which in turn leads to CD5+ tumor recurrence." (PMID 34274536, 2021). "However, a small fraction of both CD4+ and CD8+ T cell subsets recruited to the tumor microenvironment had a reduced level of CD5." (PMID 33584650, 2020). "Also, the presence of CD5+ B cells in tumor-draining lymph nodes correlated with lower staging in head and neck squamous cell carcinoma patients." (PMID 33287301, 2020).